ENTREP1 (endosomal transmembrane epsin interactor 1)
Description:
Functions as an activator of the E3 ubiquitin protein ligase ITCH in the ubiquitination of the CXCL12-activated CXCR4 receptor. Thereby, triggers CXCR4 endocytosis and desensitization, negatively regulating the CXCL12/CXCR4 signaling pathway.
Synonyms: C9orf61; FAM189A2; X123; ENTREP
Tractability: Antibody: UniProt places it where antibodies can reach, with high confidence; its Gene Ontology location is reachable by antibodies, with high confidence; UniProt predicts a signal peptide or a membrane-spanning region. PROTAC: UniProt records ubiquitination sites on it.
Gene: Protein-coding gene on chromosome 9 (69,324,567 to 69,392,592, forward strand). Ensembl gene ENSG00000135063.
Subcellular location: Early endosome membrane; Late endosome membrane; Recycling endosome membrane; Cell membrane
Gene Ontology:
Molecular function: protein binding; ubiquitin ligase activator activity
Biological process: CXCL12-activated CXCR4 signaling pathway; negative adaptation of signaling pathway; receptor internalization
Cellular component: early endosome membrane; late endosome membrane; plasma membrane; recycling endosome membrane
Genetic constraint (gnomAD): Loss-of-function variants: 33 observed, 46.61 expected, observed/expected ratio (o/e) 0.71, 90% interval 0.54 to 0.95. The upper end of that interval is the gene's LOEUF score, 0.95, which puts it in group 4 of 6, group 1 being the genes least tolerant of losing a copy. Missense variants: 580 observed, 650.2 expected, observed/expected ratio (o/e) 0.89, 90% interval 0.83 to 0.95. Synonymous variants: 246 observed, 267.81 expected, observed/expected ratio (o/e) 0.92, 90% interval 0.83 to 1.02.
Homologues: Orthologues: macaque ENTREP1 (97% identical), rat Entrep1 (88% identical), mouse Entrep1 (88% identical), pig ENTREP1 (85% identical), dog ENTREP1 (82% identical), chimpanzee ENTREP1 (81% identical), guinea pig ENTREP1 (76% identical), rabbit ENTREP1 (66% identical), tropical clawed frog entrep1 (62% identical), zebrafish fam189a2 (30% identical). Paralogues in human: ENTREP2 (29% identical), ENTREP3 (26% identical).
Diseases named in the same sentence as ENTREP1 in open-access papers:
ENTREP1 is named in the same sentence as 10 diseases in open-access papers, as found by Europe PMC text mining. Sharing a sentence is not in itself a finding about the gene and the disease.
ENTREP1 shares sentences with these, for which no sentence is quoted: breast carcinoma (4 papers); tumor (3); cancer (2); lung carcinoma (2); oral squamous cell carcinoma (2); endometrial carcinoma (1); head and neck cancer (1); pancreatic cancers (1); prostatic cancer (1); thyroid tumours (1).